COL6A2 (collagen type VI alpha 2 chain)
Diseases named in the same sentence as COL6A2 in open-access papers (continued):
Sharing a sentence is not in itself a finding about the gene and the disease.
glioma (continued). "KEGG pathway involved in glioma based on the expression level of COL6A2." (PMID 36505882, 2022). "Co-expression of PLOD1 and COL6A2 results in poor prognosis in glioma." (PMID 36505882, 2022). "Western blot was performed to examine COL6A2 protein levels in glioma U251 and normal HEB cells." (PMID 36505882, 2022). "Interestingly, COL6A2 expression was correlated with immune cell infiltration levels in glioma." (PMID 36505882, 2022). "Therefore, COL6A2 has high predictive significance for patients with glioma." (PMID 36505882, 2022). "The roles played by the immunomodulatory genes related to COL6A2 expression in glioma are unknown." (PMID 36505882, 2022). "Therefore, we investigated whether COL6A2 expression was correlated with immune cell infiltration levels in glioma." (PMID 36505882, 2022). "COL6A2 may be used as a biomarker to predict the prognosis of glioma with poor survival." (PMID 36505882, 2022). "However, the role of COL6A2 in glioma and the relationship between COL6A2 and tumor infiltrating immune cells remain unclear." (PMID 36505882, 2022). "However, the significance of COL6A2 expression in the prognosis of glioma remains unclear." (PMID 36505882, 2022). "Interestingly, most of these proteins are ECM molecules and contribute to the invasiveness of glioma cells, including FN1, TNC, LAMC1, COL1A1, EGFR, CDK6, and COL6A2." (PMID 37059730, 2023). "Besides, the TISDB database was used to explore the correlations between COL6A2 expression and lymphocytes in the GBM dataset of gliomas." (PMID 36505882, 2022). "Furthermore, in the performed co-expression of COL6A2 with the immune gene CD4, it was shown that COL6A2 and CD4 were well co-expressed in glioma tissues at different concentrations." (PMID 36505882, 2022). "Correlations between the ABCC3, COL6A2 and FAM20A genes and low-grade glioma suggested that these genes might play more complex roles in gliomas." (PMID 35456975, 2022).
bladder cancer (6 papers, 2022 to 2025). "COL6A2 encodes for a protein that is a beaded filament protein found in connective tissues and upregulation of COL6A2 has been linked with a worse prognosis for bladder cancer." (PMID 40998421, 2025). "COL6A2 may act as classical collagens by forming a physical barrier to inhibit bladder cancer growth and invasion." (PMID 37705744, 2023). "Interestingly, AKT phosphorylation was shown to be similarly affected upon COL6A3 siRNA-mediated silencing in osteosarcoma cells, also displaying a marked deregulation upon COL6A1 and COL6A2 modulation in bladder cancer cells." (PMID 37505240, 2023). "The results of the analysis showed that seven genes (VCL, FLNA, THBS1, TAGLN, ACTA2, COL6A2, and CALD1) were significantly correlated (P < 0.05) with the prognosis of bladder cancer patients, and these genes were included in the subsequent in-depth study." (PMID 41181151, 2025). "Overall, Alterations in the expression of VCL, FLNA, TAGLN, ACTA2, COL6A2, and CALD1 may play important roles in the development of bladder cancer, suggesting their potential value in early detection, molecular subtyping, and targeted therapy." (PMID 41181151, 2025). "Finally, six B-cell marker genes (VCL, FLNA, TAGLN, ACTA2, COL6A2, and CALD1) that were downregulated in bladder cancer were screened using the PPI network, survival curves, ROC curve analysis, and expression validation." (PMID 41181151, 2025).
congenital muscular dystrophy (6 papers, 2017 to 2025). A muscular dystrophy that is characterized by diminished muscle tone (hypotonia), progressive muscle weakness and degeneration (atrophy), abnormally fixed joints, spinal rigidity, and delays in reaching motor milestones such as sitting or standing unassisted. "Collagen VI-related dystrophies are a subtype of congenital muscular dystrophy caused by pathogenic variants in COL6A1, COL6A2 or COL6A3 genes affecting skeletal muscles and connective tissue." (PMID 33750322, 2021). "Mutations in the COL6A1, COL6A2 and COL6A3 genes result in congenital muscular dystrophy, arguing that collagen is critical for skeletal muscle development and function." (PMID 28755659, 2017). "In addition, mutations in COL6A1, COL6A2 and COL6A3 genes were considered causal mutations for congenital muscular dystrophy, a disease that affects connective and muscular tissue in humans." (PMID 32379844, 2020). "Causative variants in COL6A1, COL6A2 and COL6A3 genes result in skeletal muscle disorders, collectively called “collagen VI myopathies”, which represent a common type of congenital muscular dystrophy (CMD), identified in 20.24% of Italian CMD patients." (PMID 41154655, 2025).
gastric cancer (5 papers, 2011 to 2025). A primary or metastatic malignant neoplasm involving the stomach. "It confirms the risk of gastric cancer induction by chronic hepatitis B infection, which may be associated with the TLR signaling pathway mediated by CXCL9 and COL6A2." (PMID 38579038, 2024). "A previous study showed that seven collagen genes (COL1A2, COL4A1, COL6A2, COC6A1, COL4A2, and COL11A1) were highly expressed in gastric cancer tissues, consistent with our findings." (PMID 39220121, 2024).
pancreatic cancer (5 papers, 2021 to 2025). "We found that Ccn1‐deficient pancreatic cancer cells exhibit reduced expression of collagens, including Col4a1, Col4a2, Col5a1, Col6a1, Col6a2, Col6a3, and Col8a1." (PMID 40287974, 2025). "Similarly, mRNA levels of Col5a1, Col6a1, Col6a2, Col6a3, and Col8a1 were significantly reduced in Ccn1‐deficient pancreatic tumors, while Col4a1 and Col4a2 were unaffected." (PMID 40287974, 2025). "In 2001, the Pancreatic Cancer Genetic Epidemiology group (PACGENE) identified susceptibility genes in linkage studies and succeeded in finding an association of 2 genetic loci with pancreatic cancer 7p21.1 (HDAC9) and 21q22.3 (COL6A2)." (PMID 33764904, 2021).
Down syndrome (4 papers, 2019 to 2024). "Analysis of rare segmental trisomies of chromosome 21 suggested that duplication of DSCAM and the contiguous COL6A1 and COL6A2 genes may cause septal abnormalities and other Down Syndrome-related CHD lesions, including BAV." (PMID 37961530, 2023). "In a cohort of patients with Down syndrome and AVSD, variants with the highest probability of being damaging in cases compared to Down syndrome patients without cardiac defects were in the VEGF-A pathway genes COL6A1, COL6A2, CRELD1, FBLN2, FRZB, and GATA5." (PMID 31888141, 2019).
brain tumor (3 papers, 2018 to 2022). "It is very interesting to note that the concomitant upregulation of COL8A1, COL6A2 and COL6A3 has been identified as part of the adamantinomatous craniopharyngioma signature, an aggressive rare pediatric brain tumor in which calcifications are a diagnostic hallmark." (PMID 34777248, 2021). "Additionally, COL6A2 expression was also reported to be associated with high-grade astrocytomas, and gene expression profiling showed that both COL6A2 and COL6A3 are upregulated in pediatric brain tumors, including pilocytic astrocytoma, ependymoma, medulloblastoma and glioblastoma multiforme." (PMID 29728408, 2018). "In the available sources, we found no data on COL6A2 expression in brain tumor tissues collected from patients at different stages of the disease." (PMID 35454784, 2022).
hypertrophic cardiomyopathy (3 papers, 2011 to 2023). A condition in which the myocardium is hypertrophied without an obvious cause. "Notably, among these proteins, MYL2, ACTN1, MYLK, COL1A2, COL6A2, and COL6A3 have been associated with dilated cardiomyopathy and hypertrophic cardiomyopathy pathogenic processes in previous studies." (PMID 37649075, 2023).
liver fibrosis (3 papers, 2023 to 2025). "Over time, at 40w and 80w, the elevated expression of Col6a1 and Col6a2 could be associated with liver fibrosis and extracellular matrix regulation." (PMID 40537154, 2025). "The antifibrotic properties of CA were further supported by identifying many liver fibrosis-specific seed genes in PPI analysis, including TIMP2, COL6A1, and COL6A2." (PMID 37175790, 2023). "Therefore, our study investigated the role of COL6A1, COL6A2, COL6A3, and COL1A1 expressions on liver fibrosis in BA patients in Indonesia." (PMID 38041174, 2023). "Collagen VI (COL6A1, COL6A2, and COL6A3) genes, but not COL1A1, have been associated with liver fibrosis." (PMID 38041174, 2023).
melanoma (3 papers, 2019 to 2022). A malignant, usually aggressive tumor composed of atypical, neoplastic melanocytes. "Interestingly, several of these AhR‐associated genes have been involved in the aggressiveness of melanoma or other cancers and have been associated with a poor prognosis (ABCG2, COL1A1, COL6A1, COL6A2, TGFBI)." (PMID 36305167, 2022). "First, high level and activity of AhR mediates the invasive/dedifferentiated phenotype of melanoma through the direct regulation of the expression of many genes involved in invasion (COL1A1, COL6A1, COL6A2, CYR61, STC2...) and dedifferentiation phenotypes (CCL2, NTM, NUAK2, SOX9, ABCG2...)." (PMID 36305167, 2022).
myosclerosis (3 papers, 2020 to 2023). Myosclerosis is a rare, genetic, non-dystrophic myopathy characterized by early, diffuse, progressive muscle and joint contractures that result in severe limitation of movement of axial, proximal, and distal joints, walking difficulties in early childhood and toe walking. "The myosclerosis group consisted of five patients, all with an autosomal recessive inheritance and mutations in COL6A2." (PMID 37569848, 2023).
Alzheimer disease (2 papers, 2021 to 2023). A progressive, neurodegenerative disease characterized by loss of function and death of nerve cells in several areas of the brain leading to loss of cognitive function such as memory and language. "Another study demonstrated a neuroprotective role for Col6a2 against the toxicity of amyloid-β peptides in Alzheimer’s disease." (PMID 32997292, 2021).
cardiac hypertrophy (2 papers, 2011 to 2012). "A strong candidate is the Col6a2 gene located in the Mmu10 homologous region and recently found to interact with Dscam, trisomic in the Ts65Dn model, to induce cardiac hypertrophy and generate ASD-like septal defects in mouse." (PMID 22693452, 2012). "Cooperative interactions between DSCAM and COL6A2 were also observed in the H9C2 cardiac cell line and transcriptional analysis of this interaction points to genes involved in adhesion and cardiac hypertrophy." (PMID 22072978, 2011). "Further analysis will be required to determine whether DSCAM and COL6A2 contribute to ASD typical of DS and whether levels of these two genes are jointly increased in patients with inherited or spontaneous forms of cardiac hypertrophy." (PMID 22072978, 2011).
cardiomyopathies (2 papers, 2011 to 2014). "Grossman and colleagues studied the effect of the coexpression of DSCAM and COL6A2, interaction partners that are overexpressed in DS patients and are associated with cardiomyopathy." (PMID 25478570, 2014).
Cirrhosis (2 papers, 2015 to 2023). A chronic disorder of the liver in which liver tissue becomes scarred and is partially replaced by regenerative nodules and fibrotic tissue resulting in loss of liver function. "Interestingly, the collagen gene cluster expressions were significantly associated with the presence of cirrhosis (p = 0.0085, 0.04, and 0.0283 for COL6A1, COL6A2, and COL6A3, respectively)." (PMID 38041174, 2023). "Although three other genes (COL4A4, COL6A2, COL5A3) were down-regulated in these patients, our results overall support the notion that white blood cells from patients with cirrhosis are predominately prone to produce collagen." (PMID 26317806, 2015). "It is compatible with our findings that COL6A1, COL6A2, and COL6A3 expressions, not COL1A1, were strongly associated with the presence of cirrhosis." (PMID 38041174, 2023). "Interestingly, the collagen gene cluster expressions were significantly associated with the presence of cirrhosis (p = 0.0085, 0.04, and 0.0283 for COL6A1, COL6A2, and COL6A3, respectively) but not with the survival of BA patients and age at Kasai procedure." (PMID 38041174, 2023).
colorectal cancer (2 papers, 2023 to 2025). A primary or metastatic malignant neoplasm that affects the colon or rectum. "Additionally, EMT-mediated oncogenic effects have also been attributed to COL6A2 in colorectal cancer." (PMID 41323784, 2025).
craniopharyngioma (2 papers, 2019 to 2021). A benign, partly cystic, epithelial tumor of the sellar region, presumably derived from Rathke pouch epithelium. "And significantly upregulated expression of multiple genes (including COL6A2, and COL6A3) were found in adamantinomatous craniopharyngioma tumor samples." (PMID 31286980, 2019).
endometriosis (2 papers, 2020 to 2022). The growth of functional endometrial tissue in anatomic sites outside the uterine body. "Among the 15 DEPs, COL1A1, COL6A2, and NID2 are among the proteins with strong interactions, and MT2A, TYMP, COL1A1, and COL6A2 have already been associated with endometriosis." (PMID 36232817, 2022).
glioblastoma (2 papers, 2018 to 2022). The most malignant astrocytic tumor (WHO grade IV). "In addition, the expression of COL6A2 is positively correlated with regulatory T cells, type 17 T helper cells, type 1 T helper lymphocytes, etc. in glioblastoma." (PMID 36505882, 2022).
heart failure (2 papers, 2011 to 2020). Inability of the heart to pump blood at an adequate rate to meet tissue metabolic requirements. "As an example of a cooperative effect, expression of either DSCAM or COL6A2 alone resulted in ≈35% heart failure rate (N = 200 for each genotype), but when these two genes were co-expressed, the failure rate nearly doubled to 60% (N = 200; p<0.05)." (PMID 22072978, 2011). "Our networks succinctly illustrate the most influential nodes in both types of heart failure; for example, in ICM myocardium, a cluster of ECM proteins such as EFEMP1, LUM, and COL6A2 are highly influential, as is TF in the coagulation cascade." (PMID 32487995, 2020).
Hirschsprung disease (2 papers, 2022 to 2023). Hirschsprung disease (HSCR) is a congenital intestinal motility disorder that is characterized by signs of intestinal obstruction due to the presence of an aganglionic segment of variable extent in the terminal part of the colon. "For example, DSCAM cooperates with COL6A2 in congenital heart defects and may interact with BACE2 to increase susceptibility to Hirschsprung disease." (PMID 37712356, 2023). "The modulation of COL6A1 and COL6A2 expression after RUNX1 silencing could explain the causal link between trisomy 21 and an increased incidence of Hirschsprung’s disease in DS." (PMID 35356434, 2022).
keloid (2 papers, 2014 to 2016). An irregularly shaped, elevated mark on the skin caused by deposits of excessive amounts of collagen during wound healing. "Patients suffering from collagen VI related myopathies caused by mutations in COL6A1, COL6A2 and COL6A3 often also display skin abnormalities, like formation of keloids or “cigarette paper” scars, dry skin, striae rubrae and keratosis pilaris (follicular keratosis)." (PMID 25158062, 2014).
lung adenocarcinoma (2 papers, 2025). A carcinoma that arises from the lung and is characterized by the presence of malignant glandular epithelial cells. "Recent studies have shown that COL6A2 plays a key role in many tumors, especially lung adenocarcinoma, and its expression level can be used as a prognostic predictor and a potential marker for targeted therapies." (PMID 41181151, 2025).
muscle disorders (2 papers, 2019). "Collagen VI-related myopathies are a spectrum of muscular diseases with features of muscle weakness and atrophy, multiple contractures of joints, distal hyperextensibility, severe respiratory dysfunction and cutaneous alterations, attributable to mutations in the COL6A1, COL6A2, and COL6A3 genes." (PMID 30808312, 2019).
neurofibroma (2 papers, 2021 to 2025). An intraneural or extraneural neoplasm arising from nerve tissues and neural sheaths. "We discovered that the three collagen VI genes (COL6A1, COL6A2, COL6A3) are abundantly expressed in neurofibroma fibroblasts." (PMID 33413690, 2021).
osteoarthritis (2 papers, 2016 to 2023). A noninflammatory degenerative joint disease occurring chiefly in older persons, characterized by degeneration of the articular cartilage, hypertrophy of bone at the margins and changes in the synovial membrane. "Further analysis of these enriched pathways in injurious hydrostatic pressure highlighted differential expression of several genes known to be involved in osteoarthritis, such as Fgf2, Ep300, Ngf, Adam9, Igfbp3, Sox9, Comp, Col6a1, Col6a2 and Col11a1." (PMID 38144567, 2023). "In addition, several genes known to play a key role in progression of osteoarthritis (e.g., Fgf2, Ep300, Ngf, Adam9, Igfbp3, Sox9, Comp, Col6a1, Col6a2 and Col11a1) were modulated in our injurious hydrostatic pressure hip cap datasets, thereby validating this approach." (PMID 38144567, 2023).
ovarian carcinoma (2 papers, 2020 to 2022). A malignant neoplasm originating from the surface ovarian epithelium. "COL6A2 is another gene significantly upregulated in PC9GR cells, and previous reports showed that increased expression of multiple collagen genes, including COL6A2 was associated with drug resistance, tumor metastasis, and poor patient survival in ovarian cancer." (PMID 32923394, 2020). "The expression of COL11A1, COL5A1 and COL6A2 is related to overall survival (OS) rate in patients with high-grade serous ovarian cancer, and their increased expression may also lead to the resistance of ovarian cancer cell lines." (PMID 36505882, 2022).
prostate carcinoma (2 papers, 2019 to 2023). A carcinoma that arises from epithelial cells of the prostate gland. "Maybe most interestingly in regard to our data on promotion of prostate cancer cell motility by PIM1 and NFATC1, there were several genes encoding regulators of the cytoskeletal actin network (INF2, FHOD1, ACTN3, CORO1B) and cell adhesion (COL6A2, PXN, ITGA5)." (PMID 31730483, 2019).
schizophrenia (2 papers, 2023). A major psychotic disorder characterized by abnormalities in the perception or expression of reality. "Among the 7 DEGs, the TNC gene was the only gene that decreased with schizophrenia and showed a positive correlation with PI (16:0/20:4), while the other 6 DEGs (COL1A2, COL6A2, DDIT4, FGF17, GNB3, and PDGFRB) increased with schizophrenia and showed a negative correlation with PI (16:0 /20:4)." (PMID 37143779, 2023).
serous ovarian cancer (2 papers, 2022). "In serous ovarian cancer, COL6A2 was dysregulated and associated with poor prognosis through the TGFβ1 pathway." (PMID 35036081, 2022). "In addition, COL6A2 is associated with low OS in patients with high-grade serous ovarian cancer, and overexpressed in mammary cancer." (PMID 36505882, 2022).
Ullrich congenital muscular dystrophy type 1 (2 papers, 2021 to 2023). "We report a case of spontaneous mutation in the COL6A2 gene causing Ullrich congenital muscular dystrophy type 1 in a pediatric patient, expanding the phenotypic spectrum of the disease and enriching the human gene pool." (PMID 38065855, 2023). "We report a spontaneous mutation in the COL6A2 gene causing Ullrich congenital muscular dystrophy type 1 in a pediatric patient." (PMID 38065855, 2023).
adenoma (1 paper, 2024). A neoplasm arising from the epithelium. "Other frequently enriched genes in adenoma include collagen family members such as COL6A1, COL6A2, and COL6A3." (PMID 39408697, 2024).
amebiasis (1 paper, 2020). A parasitic infectious disorder caused by amoebas. "Thirty-nine DEGs were present in both datasets, 13 of which, including COL6A1, COL6A2, and COL6A3, were enriched in ECM-receptor interaction, amebiasis, focal adhesion, protein digestion, and absorption pathways." (PMID 33680912, 2020).